INS (insulin)
Diseases named in the same sentence as INS in open-access papers (continued):
Sharing a sentence is not in itself a finding about the gene and the disease.
diabetes (continued). "Metformin belongs to the biguanide family and is an insulin-sensitising drug used to control hyperglycaemia in type 2 diabetes mellitus patients." (PMID 26752241, 2016). "Reproducing these findings in humans would have an enormous clinical impact given the prevalence of diabetes mellitus type 1 and cases of diabetes mellitus type 2 that require exogenous insulin." (PMID 27211541, 2016). "An appropriate injection technique is essential for optimal insulin effect in diabetes mellitus (DM)." (PMID 27213130, 2016). "Precise insulin dosing during CSII is necessary to enable patients with diabetes to adhere to current treatment guidelines." (PMID 27457238, 2016). "For the present insulin-dependent patients with diabetes, however, the assessment of insulin resistance cannot be based on the HOMA-IR, but rather on surrogate parameters such as the daily insulin dose." (PMID 26772807, 2016). "Taken together, the study suggests that intestinal mucoadhesive devices provide an effective alternative to insulin injections for management of diabetes that can significantly improve the quality of life of patients suffering from this chronic disease." (PMID 29313019, 2016). "Here, we show that peripheral humoral and cellular immune responses against insulin are detectable in dogs with diabetes that were treated with exogenous insulin." (PMID 27031512, 2016). "This patient suffered from insulin depending diabetes with a preoperative logistic euroscore II of 15.09." (PMID 27079663, 2016). "Our studies with chicory have indicated its priority of use in early stages of diabetes when low amounts of insulin are present." (PMID 26877773, 2016). "Current insulin replacement therapy for the management of diabetes involves injections of fast-acting insulin during mealtimes, followed by longer-acting insulin injections which maintain a baseline insulin level throughout the day." (PMID 27740594, 2016). "Based on our results, we suggest removing item 6 (general diabetes subscale) and item 19 (insulin-use subscale)." (PMID 27366112, 2016). "Next, we determined insulin production capacity by assessing glucose-stimulated insulin secretion and insulin content in mice that responded to treatment and were in diabetes remission." (PMID 27874076, 2016). "Most significantly, when transplanted into immunocompromised mice, these cPB cells produced human insulin and protected mice from diabetes." (PMID 26733021, 2016). "The endocrine factor fibroblast growth factor 21 (FGF21) is being explored as a potential treatment for obesity and diabetes as it enhances insulin sensitivity and decreases triglyceride levels." (PMID 27528232, 2016). "This requires optimal diabetes management including meticulously controlled glycemia, diet, physical activity, and insulin dosages." (PMID 27556476, 2016). "Since diabetes mellitus is a common disease, the number of people receiving subcutaneous insulin is increasing." (PMID 27738545, 2016). "The ideal candidate for initiation of insulin pump therapy is a motivated patient who is knowledgeable in the important aspects of diabetes self-care and desires better glycemic control." (PMID 26742082, 2016). "The distribution of diabetes therapy was similar across both cohorts with the majority of patients clinically managed using non-insulin diabetes therapy alone (OPDP, 55.1 %; PDP, 53.7 %)." (PMID 26972690, 2016). "In T2DM patients, stiffness of carotid artery was independently related to insulin sensitivity, measured by euglycemic-hyperinsulinemic clamp, and to duration of diabetes, as well as to HbA1c." (PMID 26861377, 2016). "Because insulin inhibits tau phosphorylation through negative regulation of GSK3β and protein phosphatase 2A, diabetes promotes the formation of neurofibrillary tangles as a result of tau hyperphosphorylation, an important pathological feature of AD." (PMID 27242668, 2016).
diabetes (continued). "Participants with cirrhosis/advanced fibrosis were more likely to be male, to have diabetes, to present with higher BMI, waist circumference, fasting triglyceride, glucose and insulin levels." (PMID 26950933, 2016). "Glucose-responsive insulin delivery by closed-loop systems addresses these unmet clinical needs and aims to reduce the burden of diabetes care." (PMID 27364997, 2016). "No previous study has specifically explored the chronic effect of exenatide alone on glucose tolerance, β-cell function, and insulin sensitivity in an animal model of pre-diabetes." (PMID 27398720, 2016). "It is envisaged that these observations, together with those previously reported, will aid clinicians in better tailoring insulin treatment for patients with diabetes, particularly in regions where such data were previously unavailable." (PMID 27161418, 2016). "These cells developed insulin storage granules and, following transplantation, reversed diabetes in NOD/scid mice." (PMID 27070593, 2016). "We aimed to estimate dietary habits and diet-oriented knowledge as well as the level of physical activity in 2500 insulin-treated Polish type 2 diabetes mellitus (T2DM) patients (55.4% women)." (PMID 27703476, 2016). "Treatment with FXR agonists, GW4064, or INT-747, has been shown to reduce plasma triglyceride, glucose levels, and improve insulin sensitivity in several models of obesity and diabetes." (PMID 27733832, 2016). "In 1921, two Canadian researchers, Frederick Grant Banting and Charles Herbert Best, have successfully extracted insulin from healthy dogs, which they injected later in dogs with diabetes." (PMID 27974926, 2016). "The mean duration of diabetes prior to enrolment was 12.2 (SD 4.6) years and insulin therapy had been initiated prior to enrolment in 78 % of the studies." (PMID 27145817, 2016). "Collectively, these mechanisms help to maintain normal glucose levels via counter-regulatory effects of insulin and glucagon on hepatic gluconeogenesis and dysfunction of these mechanisms leads to hyperglycemia in diabetes." (PMID 27990298, 2016). "There are few published papers on the use of insulin in patients with cystic fibrosis prior to overt diabetes." (PMID 26994743, 2016). "High levels of GADAb, antithyroid peroxidase antibody (TPOAb), the presence of autoantibodies against the middle epitope of GAD65 and multiple anti-islet autoantibodies have been reported to be predictive markers for insulin-requiring diabetes." (PMID 27177031, 2016). "These responses make leptin a promising biological target for a complementary therapy to the traditional insulin treatments for diabetes and obesity." (PMID 27055280, 2016). "The most common tweets were the terms including the term or hashtag diabetes, followed by insulin and glucose, and then finally references to the type of diabetes (ie, type 1 or type 2 diabetes)." (PMID 30291053, 2016). "Diabetes progression was evaluated according to the levels of glucose, insulin and glycated hemoglobin in blood samples." (PMID 26983784, 2016). "Diabetes mellitus is defined as a group of metabolic diseases characterized by hyperglycemia resulting from defects in insulin secretion, insulin action, or both or insulin resistance." (PMID 27761427, 2016). "The objective was to identify barriers to insulin progression in individuals with type 2 diabetes mellitus (T2DM) in LA countries (Mexico, Brazil, and Argentina)." (PMID 27453733, 2016). "Both micro- and macroangiopathies, in addition to hyperlipidemia, male gender, longer diabetes duration, and insulin use, play significant roles in the etiology of ischemic stroke." (PMID 26989695, 2016). "Using the precise sequence information of INS/IL-1α motif, development of a neutralizing antibody against the ligands and receptors will shed light on the specific role of pINSd and IL-1α in diabetes." (PMID 27226621, 2016).
diabetes (continued). "Impairment of insulin signaling on diabetes mellitus has been related to cardiovascular dysfunction, heart failure, and sudden death." (PMID 27014078, 2016). "Of note, Prdx6 just recently has been identified as an important player in diabetes pathology as knockout of Prdx6 led to impaired insulin production and reduced muscular glucose up-take in mice." (PMID 26324419, 2016). "Insulin and C-peptide levels in diabetes are higher than in healthy controls, while low levels of insulin and C-peptide are seen in PDAC-associated diabetes." (PMID 27276680, 2016). "Insulin-secreting beta cells play an essential role in maintaining physiological blood glucose levels, and their dysfunction leads to the development of diabetes." (PMID 27841257, 2016). "Insulin sensitivity can be improved through vitamin D supplementation in individuals with pre-diabetes." (PMID 27916865, 2016). "Thiazolidinediones (TZDs), a class of drugs known to improve insulin sensitivity, are commonly used for the treatment of diabetes." (PMID 25976368, 2016). "Diabetes mellitus is a chronic metabolic disorder characterized by hyperglycemia due to inadequate insulin secretion, ineffective action or a combination of these." (PMID 26923830, 2016). "Streptozotocin is one of the most common reagents used to prepare diabetes experimental models; this reagent can selectively destroy pancreatic islet β cells to reduce insulin secretion and increase blood glucose of rats." (PMID 26837497, 2016). "Objective was to qualify the subchronic STZ-model together with the insulin dosing regimen as a suitable model for the study of type 1 diabetes drugs in combination with insulin and possible longterm complications of diabetes-like nephropathy." (PMID 27253523, 2016). "The expression levels of miR-194 were validated by qPCR, demonstrating a 50% reduction in expression in the skeletal muscle of individuals with pre-diabetes and diabetes and a 25% decrease in the skeletal muscle of insulin resistant rats." (PMID 27163678, 2016). "Diabetes mellitus is a group of metabolic diseases characterized by hyperglycemia resulting from defects in insulin secretion, insulin action, or both, which eventually leads to a series of complications in various organs." (PMID 26901059, 2016). "In our study median time to insulin initiation increased by 2 months when we excluded patients with the same dates for insulin prescription and diabetes diagnosis." (PMID 27861488, 2016). "adjusted for: scholling, blue collar worker, use of insulin, duration of diabetes, SAHLPA-18 score; Variance analysis test (ANOVA) to compare statistical significance of the models." (PMID 28076599, 2016). "It has been reported that diabetes drugs thiazolidinediones increase insulin sensitivity by special targeting to a site (mTOT), which in turn inhibits MPC." (PMID 27835892, 2016). "Overall, 46% had claims for metformin, 23% had claims for insulin, and 29% had claims for sulfonylureas, with smaller percentages of patients having claims for other diabetes single therapy or combination medications." (PMID 27895533, 2016). "The MCI group and the control group were well matched in terms of age, gender distribution, educational level, smoking history, drinking history, BMI, hypertension prevalence, diabetes duration, insulin use, and ACEI or ARB use (p > 0.05)." (PMID 28066203, 2016). "SMBG can be considered the primary technique to assess the effectiveness of the patient glycemic control plan and the satisfaction with a BGM should be a key point in the management of diabetes, particularly among insulin-treated patients." (PMID 27625706, 2016). "Insulin sensitivity was significantly reduced in patients with impaired glucose tolerance or diabetes compared to controls." (PMID 27872738, 2016). "The pathophysiology of diabetes commences when the insulin level is inadequate to decrease the blood glucose level and the patient develops hyperglycemia." (PMID 27092078, 2016).
diabetes (continued). "Variants in GC have previously been reported in association with T2DM and quantitative traits connected with diabetes mellitus, including plasma glucose, insulin concentrations, and insulin resistance." (PMID 27636996, 2016). "In a recent NHS cross-sectional audit of inpatient diabetes care in over 200 UK hospitals 39.8 % of patients had at least one medication management, insulin or prescription error during their inpatient stay." (PMID 26956764, 2016). "This is surprising because bone disease in diabetes mellitus is probably as old as the disease itself since descriptions of bone disease in diabetes can be traced as far back as the 1920s and is as old as insulin itself." (PMID 27777961, 2016). "In all participants, the unadjusted model showed that PAD was associated with increase in age, BMI, mean BP, female gender, having diabetes or hypertension, alcohol intake, second-hand smoking and use of insulin." (PMID 27093857, 2016). "In fact, no previous study has specifically explored the effect of exenatide alone on glucose tolerance, β-cell function, and insulin sensitivity in the pre-diabetes state, using well accepted methods, under controlled conditions." (PMID 27398720, 2016). "Insulin gene mutations, either dominant or recessive, can cause permanent neonatal diabetes mellitus (INS/PNDM), which is defined as diabetes with onset within 6 months of birth." (PMID 26239141, 2016). "Here, we review the converging evidence from AD, TBI and diabetes research linking insulin insensitivity to neurodegeneration." (PMID 30202553, 2016). "Estimating the amount of insulin to deliver is one of most challenging and essential tasks in the everyday life of individuals with diabetes." (PMID 27170498, 2016). "Our data also show higher prevalence of CAD in subjects on insulin therapy and an association between the presence of CAD and both insulin use and duration of diabetes." (PMID 26861208, 2016). "In the outpatient setting the obese patients with poorly controlled insulin treated type 2 diabetes mellitus should be rigorously assessed towards malignancies, particularly breast cancer in women and colorectal cancer in men." (PMID 27724912, 2016). "In RECORD-1, 63% of patients with hyperglycemia were taking medication to control their diabetes at the start of the study (metformin, 18%; sulfonamide urea, 15%; and insulin, 30%)." (PMID 27287020, 2016). "Animal models and studies on patients have extensively documented impaired insulin signalling and degradation in AD and diabetes." (PMID 27240327, 2016). "Diabetes patients are usually started on a low dose of insulin and their dose is adjusted or “titrated” according to their blood glucose levels." (PMID 26187303, 2015). "South Asians are also characterized by a unique metabolic profile with higher insulin levels, a greater degree of insulin resistance and a higher prevalence of diabetes." (PMID 26020947, 2015). "Diabetes mellitus (DM) is a disease of metabolic dysregulation, characterized by chronic hyperglycemia due to insufficient insulin action." (PMID 25546164, 2015). "As Pdx1-dnBmpr1a and insulin promoter-derived Bmpr1a-deleted mice develop diabetes at 2–3 months of age, we also performed intraperitoneal glucose challenge in our pBmpr1aKO mice at 3 months of age." (PMID 26187948, 2015). "Plasma samples from 16 insulin-resistant morbidly obese subjects, of whom 14 had diabetes, were subjected to global metabolomics and lipidomics analysis at pre-surgery and 4 and 42 days after RYGB." (PMID 25946120, 2015). "Normally, insulin, a hormone produced by the β-cells of the pancreas, lowers blood glucose levels and its absence or insufficient production results in diabetes." (PMID 26848337, 2015). "After confirmation of diabetes, crocin (30 mg/kg, i.p.), safranal (1 mg/kg, i.p.)(alone or in combination with insulin) and insulin (5 IU/kg, s.c.)were administered for eight weeks." (PMID 26468467, 2015).
diabetes (continued). "Biomarkers of obesity (leptin, adiponectin), diabetes (glucose, insulin), inflammation (C-reactive protein, Interleukin-6, surface tumor necrosis factor receptor (sTNFR) I & II) and oxidative stress (F2-isoprostanes) were measured in stored blood samples." (PMID 26380096, 2015). "Insulin pumps require vigilance on the part of the patient and their use should be overseen by endocrinologists and experienced diabetes educators." (PMID 28702221, 2015). "Particularly appealing is the over-representation of the KEGG pathways “Type II diabetes mellitus (T2D)” and “Insulin signaling pathway”, which suggests a possible role of cell senescence in regulating insulin sensitivity and diabetes." (PMID 26583757, 2015). "The available drugs for diabetes, insulin or oral hypoglycemic agents have one or more side effects and search for new antidiabetic drugs with minimal or no side effects from medicinal plants is a challenging for us." (PMID 25925864, 2015). "Diabetes mellitus encompasses a heterogeneous group of disorders characterized by insulin hyposecretion and/or insensitivity." (PMID 26347423, 2015). "The main purpose of diabetes care and treatment is to maintain insulin activity and blood glucose within normal limits, thereby reducing vascular and neuropathic complications." (PMID 26005688, 2015). "Insulin signalling sensitizers (e.g. pioglitazone and metformin) that commonly used in treating diabetes have proven clinically beneficial in improving biochemical indices in NAFLD patients." (PMID 25658428, 2015). "All of the interviewees stated that they were aware of the necessity of taking insulin injections, following the diet and checking their blood sugar regularly for diabetes management." (PMID 26005688, 2015). "As a result, treatment needs to be implemented early and aggressively, yet even on insulin therapy such patients can show worse diabetes control." (PMID 26239144, 2015). "Glycated hemoglobin (HbA1c) is currently used to diagnose diabetes mellitus, while insulin has been relegated to research." (PMID 26241903, 2015). "Patients with diabetes received from 0.1 to 1.3 units of insulin/kg of body mass (mean 0.76 ± 0.29)." (PMID 25952029, 2015). "Yet most cases of DKA are preventable through proper insulin management and early detection of diabetes for new patients." (PMID 26323283, 2015). "We conducted a proof-of-concept interventional study of inpatients with diabetes mellitus who had hospital orders for basal-bolus or sliding scale insulin." (PMID 26429339, 2015). "The literature has shown that the majority of diabetes patients in most resource-poor countries are dying because they cannot access insulin." (PMID 25890162, 2015). "All patients were categorized into one of four groups: CF, Diabetes (type 1, insulin dependent), CFRD or healthy controls and their diagnoses confirmed by a specialist physician." (PMID 25754382, 2015). "Diabetes mellitus is characterized jointly by hyperglycemia and hyperinsulinemia that make insulin more prone to be glycated and evolve insulin advanced glycation end products (Insulin- AGE)." (PMID 26311627, 2015). "The aim of the present study was to evaluate glycemic variability using the CGM system in pediatric patients with insulin-treated diabetes in WFS versus pediatric patients with autoimmune T1D." (PMID 25916214, 2015). "Zinc plays a key role in the synthesis and action of insulin, both physiologically and in the pathological state of diabetes (Chausmer, 1998 ▶)." (PMID 26468459, 2015). "The MAGE measured by CGMS in the group of diabetes patients treated with insulin alone (7.50 ± 3.28 mmol/L) was significantly higher than the group with added acarbose (5.56 ± 2.16 mmol/L, P = 0.044)." (PMID 26640487, 2015). "Compared to patients with normal glucose tolerance (NGT), insulin sensitivity was lower and insulin secretion impaired in patients with disturbances in glucose metabolism such as prediabetes or newly diagnosed diabetes mellitus." (PMID 26398489, 2015).